IL6 (interleukin 6)
Diseases named in the same sentence as IL6 in open-access papers (continued):
Sharing a sentence is not in itself a finding about the gene and the disease.
COVID-19 (continued). "Here we show that human blood monocytes can effectively sense SARS-CoV-2, and subsequently respond by substantial upregulation of the proinflammatory cytokines TNF, IL-1β and IL-6, which comprise the core hyperinflammatory signature seen in severely ill COVID-19 patients." (PMID 39963132, 2025). "Elevated cytokines IL-6, IFN-γ, and TNF-α have been associated with severe COVID-19 outcomes." (PMID 41035684, 2025). "Moreover, patients with MIS present more often neutrophilia and thrombocytopenia than lymphocytopenia and have higher levels of pro-inflammatory biomarkers (e.g. CRP and IL-6) within 48 h from admission compared to patients with COVID-19." (PMID 39775145, 2025). "By lowering proinflammatory cytokines such as IL-6 and TNF-a, SGLT2is could mitigate the cytokine storm associated with severe COVID-19 cases." (PMID 40136608, 2025). "That study revealed an enriched antigen-specific Th1-type cytokine profile in recovered COVID-19 patients, whereas individuals with Long-COVID exhibited significantly elevated levels of inflammatory cytokines IL-1β and IL-6 compared to the unexposed group, two months after acute infection." (PMID 40406109, 2025). "IL-6 levels are significantly elevated in COVID-19 patients." (PMID 40699865, 2025). "Escalating concentrations of recombinant spike can activate human lung macrophages, triggering the production of proinflammatory cytokines that mirror the “cytokine storm” signature observed in clinical COVID-19 cases (IL-2, IL-4, IL-6, IL-1β, IL-8, IFN-γ, TNF-α, and CXCL10)." (PMID 41012643, 2025). "Previous studies have already shown that individuals with COVID-19 had high levels of some inflammatory mediators in more severe cases of the disease, such as C-reactive protein, D-dimer, bilirubin, urea, and IL-1β, IL-6, IL-8, IL-10, IL-18, IFN, TNF-α cytokines." (PMID 39861879, 2025). "Likewise, 61% of COVID-19 patients with elevated proinflammatory cytokines (IL-6 and IL-10) had a fatal outcome." (PMID 40508859, 2025). "IL-6, a cytokine intimately involved in the inflammatory cascade, also exhibits a notable correlation (r = 0.45, p < 0.001), underscoring its prognostic relevance in COVID-19." (PMID 40299484, 2025). "The production of IFN-β by perivascular macrophages and damaged endothelial cells in skin lesions of COVID-19 patients were demonstrated, alongside with elevated levels of IL-1, IL-6, and TNF-α, resulting in a disrupted type I IFN and pro-inflammatory cytokine response." (PMID 40649826, 2025). "This shows that COVID-19 treatment needs to be individualized and especially patients with high IL-6 may benefit from tocilizumab treatment." (PMID 39210228, 2025). "Patients in group B had a shorter length of stay, whereas COVID-19 patients experienced prolonged hospitalization, which could have influenced IL-6 dynamics." (PMID 40004007, 2025). "A study evaluating the efficacy of TCZ treatment in COVID-19 based on initial IL-6 levels may elucidate this discrepancy." (PMID 39955435, 2025). "While prior meta-analyses and systematic reviews have primarily focused on the role of cytokines or individual interleukins, such as IL-6, in predicting COVID-19 severity, there is limited consolidated evidence on both S100 proteins and interleukins as a combined biomarker profile." (PMID 41585373, 2025). "In addition, an imbalance in the systemic inflammatory response, marked by an increased IL-6/IL-10 ratio, is one of the possible factors contributing to the severity of primary open-angle glaucoma, gastric cancer, or COVID-19 patients." (PMID 40430444, 2025). "In a cohort of patients where NTIS appeared to be a frequent thyroid abnormality, our study uncovered important differences in biomarker networks and thyroid hormone adaptive responses orchestrated by inflammatory signals such as IL-6, especially in critically ill COVID-19 patients." (PMID 41286140, 2025).
COVID-19 (continued). "However, several patients that died with severe COVID-19 had relatively low antibody titers and very high IL-6 concentrations, implying an inverse correlation between the inflammatory response and neutralizing antibody titer." (PMID 39969178, 2025). "Furthermore, in severe cases of COVID-19, elevated levels of IL-1β and IL-6 cytokines have been observed." (PMID 40072090, 2025). "In addition to elevated levels of high-sensitivity C-reactive protein (hs-CRP), COVID-19 patients with myocardial injury also presented with low lymphocyte count, and high levels of IL-6, IL-8, N-terminal pro-B-type natriuretic peptide (NT-proBNP) and TNF-α." (PMID 40438117, 2025). "In addition, recent reports have described increased IL-6 production in individuals who received COVID-19 mRNA vaccines." (PMID 41200189, 2025). "Tocilizumab, an IL-6 inhibitor, was granted authorization by the US Food and Drug Administration for severe COVID-19 patients already on corticosteroids, but its effectiveness remains unclear." (PMID 41322858, 2025). "In summary, IL-6 rs1800795 and TNF-α G-308 A, as common SNPs in both diseases, may explain the genetic factors underlying COVID-19-induced AIH at the genomic level." (PMID 39958350, 2025). "Specifically, higher levels of IL-1β, IL-6, IL-8, IL-10, IL-18, and TNFα have been found in patients with severe disease and complications, such as acute respiratory distress syndrome (ARDS), which are the main cause of mortality in COVID-19." (PMID 40788382, 2025). "They found that high levels of IL-6 and a large number of ACE-2 receptors in adipocytes may be associated with an unfavorable prognosis and higher severity of COVID-19 in obese patients." (PMID 40904859, 2025). "There are also studies suggesting that the inflammatory response induced by COVID-19 may lead to elevated levels of inflammatory markers such as IL-6, which play a key role in angiogenesis and metastasis and may accelerate the development of lung cancer." (PMID 40236655, 2025). "From a clinical point of view, hs-CRP and inflammatory cytokines, such as IL-6, may be important markers of COVID-19 severity and the development of PCS syndrome." (PMID 40950970, 2025). "However, pediatric cases progressing to severe COVID-19 show distinct immunological patterns: decreased T cell and natural killer cell populations, impaired interferon responses, and elevated IL-6 and IL-10 levels compared to mild cases." (PMID 40370452, 2025). "Conversely, compared to G/G-C/C, the IL-6 -174 G/C genotype may offer some protection against adverse COVID-19 progression (p = 0.03; OR = 0.41, 95% CI 0.18-0.96)." (PMID 39958350, 2025). "The immune response depends on the amount of SARS-CoV-2 at the time of infection, where we showed that the Ct values of RT-qPCR diagnostics were negatively correlated with IL-6 in male COVID-19 patients, indicating that increased IL-6 corresponds to higher viral load." (PMID 40868247, 2025). "In addition to the critical role of IL-1β, IL-6 levels have also been shown to correlate with poor prognosis in COVID-19 patients." (PMID 41233351, 2025). "IL-6 levels were determined in 22 COVID-19 and 28 non-COVID-19 patients." (PMID 41233786, 2025). "The rapid drop in IL-6 (from >50,000 pg./mL down to 285 pg./mL in 24 h), ferritin reduction and early hemodynamic stabilization matches what’s been seen in septic shock and COVID-19 studies." (PMID 41488066, 2025). "Single nucleotide polymorphisms (SNPs) in the TNF-α, IL-6, IL-8, IL-10, CCL5 and CXCL6 genes have been found to be associated with COVID-19 severity, suggesting that SNPs could help explain COVID-19 outcomes." (PMID 40881695, 2025). "Furthermore, the IL-6 rs1800795 GG genotype and the IL-6R (rs12083537) GG genotype can predict COVID-19 mortality." (PMID 39958350, 2025). "Another study found that IL-1 and IL-6 blockers did not shorten time to clinical improvement in COVID-19 patients who had a low baseline mortality risk." (PMID 40612950, 2025).
COVID-19 (continued). "Tocilizumab is amonoclonal antibody inhibitor of interleukin-6, initially used to treatrheumatoid arthritis and later tested for COVID-19 treatment, which may havea protective effect on AKI." (PMID 41493315, 2025). "These, in association with our findings of KA effect on SARS-CoV-2 replication, are a combination that is particularly significant considering the pathogenesis of COVID-19, with the disease resulting in increased IL-6 and other inflammatory cytokines in the patients’ blood." (PMID 40415937, 2025). "Notably, interleukin-6, lymphocyte count, hs-troponin T, ferritin and D-dimers emerged as particularly significant indicators of COVID-19 severity." (PMID 40283188, 2025). "Concerning the possible association between the IL-6/KL-6 ratio and lung damage as assessed by CT, this could be predictive of the severity of lung involvement in COVID-19 like IL-6 or KL-6." (PMID 40397955, 2025). "COVID-19-related TM may result from a similar process, where molecular mimicry and cytokine-mediated inflammation (particularly elevated IL-6 and TNF-α levels) contribute to spinal cord damage." (PMID 41510433, 2025). "However, the specific mechanism by which IL-6 acts in COVID-19-related OD needs to be further explored." (PMID 40420944, 2025). "COVID-19 symptoms, influenced by IL-1 and IL-6, might also occur alongside diabetes complications, although timely treatment could show elevated biomarkers in discharged patients, either without symptoms or with atypical symptoms." (PMID 40134446, 2025). "Sirolimus may prevent the progression of COVID-19 to severe forms by downregulating the senescence-associated secretory phenotype (SASP), mTOR-NLRP3-IL-1β axis, IL-6 pathway, and the number of senescent T cells." (PMID 40808960, 2025). "High levels of IL-6 and IL-10 could be related to the overactivation of Th2 immune-mediated responses, resulting in disease progression to the critical COVID-19 stage or even death." (PMID 40508859, 2025). "Higher levels of IL-6 are related to severe COVID-19 and adverse prognosis." (PMID 40438117, 2025). "A study of 1953 patients with COVID-19 showed elevated levels of IL-6, IL-8, TNF-α and IL-1B." (PMID 40236655, 2025). "Furthermore, increased levels of IL-6 and IL-10 correlate with COVID-19 severity, and the dysregulated Th1 immune response in critically ill patients reinforces this theory." (PMID 40690446, 2025). "IL-6 serum levels were increased between COVID-19 patients and humanized monoclonal anti-IL-6 receptor tocilizumab administration was efficient Feel secure when caring with COVID-19 patients." (PMID 40895261, 2025). "Given the evidence supporting adjunctive anti-IL-6 therapy in severe COVID-19, we sought to review evidence that targeting IL-6 might have a role in pleural infection." (PMID 40819633, 2025). "The pathogenesis of COVID-19 involves a complex group of mediators, including IL-6 and IL-1029." (PMID 41203712, 2025). "In our cohort, we found a significant increase in IL-6 at admission in moderate COVID-19 patients." (PMID 40508859, 2025). "Studies have shown that systemic administration of ozone in COVID-19 patients shortened hospitalization time, reduced proinflammatory cytokine levels (IL-2, IL-6, IL-8, TNF-α), and simultaneously increased concentrations of the anti-inflammatory cytokine IL-10." (PMID 41614780, 2025). "While IL-6 may also reflect the systemic inflammatory response characteristic of severe COVID-19, its presence in urine points toward an active lung–kidney crosstalk." (PMID 40283616, 2025). "Additionally, high IL-6 levels were found in PBMNC samples from patients with long COVID-19 (GEO: GSE224615;) compared to uninfected PBMCs." (PMID 40055791, 2025). "This study reports that COVID-19 patients in the ICU had the highest mean levels of IL-6 and zinc." (PMID 40756075, 2025).
COVID-19 (continued). "The cytokine storm, a hallmark of severe COVID-19, is characterized by the uncontrolled release of pro-inflammatory cytokines such as tumor necrosis factor-alpha (TNF-α), interleukin-1 beta (IL-1β), and interleukin-6 (IL-6)." (PMID 40002898, 2025). "In addition to tocilizumab, various additional monoclonal antibodies (mAbs) that have the potential to inhibit the physiological impacts of IL-6 are being evaluated in clinical studies for the treatment of COVID-19, including sarilumab, siltuximab, sirukumab." (PMID 40438117, 2025). "The therapeutic effects of immune blockers in COVID-19, such as IL-6 inhibitors, have raised questions about whether their benefits stem primarily from suppressing inflammation, reducing hypercoagulation, or a combination of both." (PMID 40612950, 2025). "Both cardiac biomarkers (High-sensitivity Troponin T (Hs-TnT)), and N-terminal pro–B-type natriuretic peptide (NT-proBNP)), and inflammatory biomarkers (Interleukin-6 (IL-6) and Procalcitonin (PCT)) have been associated with (COVID-19) disease severity and mortality." (PMID 39779607, 2025). "A recent study found that patients with acute COVID-19 who later developed Long COVID had higher IL-6 levels during the acute phase indicating than those who fully recovered, demonstrating that carrying the IL-6R AA genotype had a higher risk of developing Long COVID." (PMID 40087795, 2025). "These previous studies, reporting lower plasma concentrations of several pro-inflammatory cytokines (including IL-6) in COVID-19 patients verses those with ARDS, cytokine release syndrome or in septic patients, have cast doubt on the very existence of the cytokine storm in COVID-19 for some authors." (PMID 40397955, 2025). "Additionally, it was seen that of the many hallmarks inflammatory mediators analyzed, only IL-1, IL-6, and TNF had a significant association with post-acute sequelae of COVID-19 such as fatigue, dyspnea, and issues with concentration." (PMID 40333142, 2025). "The pro-inflammatory cytokine surge in COVID-19, especially IL-6 and TNF-α, may further contribute to tissue damage and ulcer formation." (PMID 40546542, 2025). "The results revealed that polymorphisms in the IL6, IL6R, IL1α, IL1R, IFNγ, TNFα, CRP, VDR, VDBP, and ACE2 genes are the most significant genetic factors influencing COVID-19 prognosis, particularly in terms of the risks of COVID-19 pneumonia, mortality, rehospitalization, and associated mortality." (PMID 40869297, 2025). "Maternal immune activation during COVID-19, driven by elevated IL-6, IL-8, TNF-α, and other pro-inflammatory mediators such as IL-1β, disrupts foetal neurodevelopment by priming microglia, altering dopaminergic/γ-aminobutyric acidergic (GABAergic) pathways, and activating complement cascades." (PMID 40806558, 2025). "Therapeutic strategies in COVID-19 have also evolved, with widespread use of corticosteroids, IL-6 inhibitors, IL-1 blockers, and antiviral agents, all of which may affect inflammation, thrombosis, and secondary infection risk." (PMID 41463074, 2025). "A recent scoping review suggests that periodontitis and COVID-19 may independently raise serum levels of IL-1β, IL-6, and TNF-α in the same individual." (PMID 41463036, 2025). "For SLE and COVID-19 severity, IL-6 and IL-10 emerged as key genes (DC>8.0, BC>17.0, and CC>0.7)." (PMID 40643149, 2025). "A similar study found a strong association between COVID-19 severity and elevated levels of C-reactive protein (CRP), procalcitonin, interleukin-6, neutrophils, hs-troponin T, lactate dehydrogenase (LDH), ferritin and D-dimers, along with decreased levels of albumin, lymphocytes and platelets." (PMID 40283188, 2025). "Moreover, they exhibited promising anti-inflammatory effects through TNF-α: TNFR2 inhibitory activity in addition to their inhibitory effect on TNF-α and IL-6, the predominant cytokines in COVID-19-related cytokine storm via cell-based anti-inflammatory assay." (PMID 39854441, 2025).
COVID-19 (continued). "The documented nonlinear association between IL-6 and NT-proBNP further highlights the biological link between systemic inflammation and myocardial strain in COVID-19." (PMID 41303223, 2025). "Notably, findings from a systematic review and meta-analysis indicate the increased IL-6 levels alone are correlated with long COVID-19." (PMID 40872762, 2025). "Moderate COVID-19 pneumonia patients had higher levels of IL-6 compared to non-COVID-19 patients." (PMID 40508859, 2025). "In PLWH/COVID-19, elevated IL-6, IL-5, IL-9, and IL-15 interleukins compared to COVID-19-only could induce a strong immune response in these patients." (PMID 41516165, 2025). "Conversely, anxiety may impact the function of five COVID-19 regulators, including the activation of four proteins (IL6, angiotensin 2, TNF, and IL10) and the inhibition of one protein (DPP4)." (PMID 40766923, 2025). "Also, IL6 expression remains is a crucial immune process that is central to the pathophysiology of COVID-19 in lung and brain tissue, particularly in the latter where plays a role in exacerbating hemorrhagic and thrombotic events." (PMID 41141600, 2025). "Furthermore, IL-6 can trigger T cell apoptosis through the Fas-FasL interaction, a mechanism further corroborated by autopsy findings in COVID-19-related ARDS cases." (PMID 40661964, 2025). "Therefore, the objective of this study was to determine the clinical characteristics and serum levels of IL-6 and the micronutrient zinc as biomarkers in patients with COVID-19 according to their hospital care conditions in Lima, Peru." (PMID 40756075, 2025). "This integrative strategy not only enabled the identification of IL-17, alongside IL-6, as an independent predictor of COVID-19 severity but also uncovered structural motifs—particularly Asparagine (Asn) and cysteine (Cys) residues—shared between viral proteins and host inflammatory mediators." (PMID 41184328, 2025). "Furthermore, the majority of patients with severe COVID-19 exhibit markedly elevated serum levels of pro-inflammatory cytokines, including interleukin (IL)-6, IL-1β, IL-2, IL-8, IL-10, interferon (IFN)-α, IFN-γ, and tumor necrosis factor (TNF)." (PMID 41200104, 2025). "This hyperinflammatory state is characterized by the overproduction of pro-inflammatory cytokines such as IL-6, TNF-α, and IL-1β, which can cause widespread tissue damage and contribute to the severe manifestations of COVID-19, such as acute respiratory distress syndrome (ARDS)." (PMID 40094929, 2025). "We suggest that both IL-6 and IL-10 might be useful biomarkers to improve diagnosis and severity stratification in COVID-19 patients and possibly tailor treatment accordingly." (PMID 40508859, 2025). "IL-6 is a key pro-inflammatory cytokine in the pathogenesis of COVID-19." (PMID 41156098, 2025). "—TNF-α and IL-6—play significant roles in several inflammatory diseases including COVID-19." (PMID 40121473, 2025). "Early data suggest that IL-6 inhibitors may improve outcomes in COVID-19 patients by reducing respiratory complications and potentially aiding recovery in co-infected burn patients by minimizing immune system overactivation." (PMID 40794529, 2025). "The observed IL-6-TNF correlation likely reflects shared upstream activation (e.g., via monocyte/macrophage pathways), a pattern frequently associated with more severe COVID-19 forms." (PMID 41357245, 2025). "Furthermore, elevated levels of inflammatory cytokines, particularly IL-6, have been reported to correlate with COVID-19 severity." (PMID 40421029, 2025). "Apoptosis mediated by the FAS-FASL pathway, which is sustained by the continual stimulation of cytokines such as TNF and IL-6, may have been involved in the lymphocyte death seen in the spleens of the COVID-19 patients studied herein." (PMID 41210940, 2025).